PPARD (peroxisome proliferator activated receptor delta)
Diseases named in the same sentence as PPARD in open-access papers (continued):
Sharing a sentence is not in itself a finding about the gene and the disease.
tumor (continued). "This suppression of COX-1- PPARδ signaling by aspirin lead to compromised tumor growth in mice; this result suggests the importance of this pathway to stimulate tumor growth and offers a promising target for ovarian cancer treatment." (PMID 32982722, 2020). "In this study, we found that the acidic tumor microenvironment can reduce VDR expression via PPARD and prevent the accumulation of VDR in the nucleus." (PMID 32900990, 2020). "In contrast, PPARδ−/− mice inhibit DSS-induced colonic inflammation and colitis-associated tumor growth, which is associated with inhibition of VEGF expression." (PMID 28948004, 2017). "In contrast, PPARδ-mediated tumor development is inhibited by nitric oxide donating aspirin (NO-ASA)." (PMID 28948004, 2017). "Peroxisome-proliferator-activated receptors (PPARs) are nuclear hormone receptors including PPARα, PPARδ and PPARγ, which play an important role in regulating cancer cell proliferation, survival, apoptosis, and tumor growth." (PMID 28948004, 2017). "In Apcmin mice, PGE2 treatment promoted cell survival and distinctly increased tumor burden, which was mediated by the transactivation of PPARδ through PI3K/Akt signaling." (PMID 28852270, 2017). "Even though the PPARs family contains PPARα, PPARγ and PPARδ, they serve as different functions in tumor development." (PMID 28948004, 2017). "PPARD agonist and mutant RXRA confer growth-factor-independent growth to urothelium in the context of tumor suppressor loss." (PMID 29143738, 2017). "This can be envisioned to result in part from competition between the tumor promoting effects of PPARδ and the tumor suppressor effects of PPARγ." (PMID 28077942, 2016). "PPARδ expression is negatively regulated by the APC tumor-suppressor pathway through the β-catenin/TCF-lef responsive elements in its promoter." (PMID 23875171, 2013). "The present study has examined the effect of PDK1 transgene expression on mammary carcinogenesis, and how it impacts the tumor promoting effects of PPARδ activation." (PMID 21297860, 2011). "This animal model will therefore be useful to delineate the role of PPARδ in tumor initiation and progression and as a possible target for early intervention." (PMID 21318167, 2010). "The selective PPARδ agonist GW501516 acts as a tumor promoter in mammary carcinogenesis and colon tumorigenesis, whereas disruption of PPARδ expression blocks mammary and colon tumorigenesis." (PMID 21318167, 2010). "And, third, changes in tumor response, PPARδ, and cytokineticparameters (apoptosis and necrosis) are closely correlated and mechanisticallycongruent." (PMID 18528523, 2008). "In anotherexample, the onset of tumor formation, tumor size, and tumor multiplicity ofthe skin wassignificantly enhanced in PPARδ-null mice compared with wild-type mice." (PMID 18528523, 2008). "PPARδ agonists stimulate proliferation and survivalof cancer cells in vitro andpromote tumor growth in mice." (PMID 18551186, 2008). "Additional evidence pointing to atumor promoting function of PPARδ comes from experiments in mice wheredisruption of PPARδ decreased tumorigenicity of cancer cells innude mice and PPARδ activation increased tumor growth." (PMID 18551186, 2008). "In murineknockout experiments, targeted removal of a hub node (PPARδ) of the angiogenicnetwork markedly impaired angiogenesis and tumor growth." (PMID 18528523, 2008). "PPARδ has been recently identified as a criticalnode in a tumor angiogenic network linking angiogenesis to inflammation andcarcinogenesis." (PMID 18551186, 2008). "Firstly a study of matched human tumour and normal intestinal tissues found reduced levels of PPARδ expression in the tumours." (PMID 16672050, 2006). "With regard to human tissue, increased expression of PPARδ was first reported in a small set of CRC tumours." (PMID 16969348, 2006). "Furthermore, PPARD was found to be highly expressed in tumor tissues compared to adjacent tissues based on the TCGA database." (PMID 39922804, 2025).
tumor (continued). "In line with this, our data suggest that PPARδ’s role in the interaction between tumor cells and TAMs may be bidirectional, as we observed PPARD upregulation and activation in response to signals from TAMs." (PMID 40607925, 2025). "Intriguingly, single-cell RNA sequencing (scRNA-seq) identified PPARδ as a directly druggable upstream target, which integrates both starvation and tumor microenvironmental signals to modulate cellular metabolism and invasiveness via increasing the MYC/PGC1A ratio." (PMID 40607925, 2025). "Finally, we observed that genetic or pharmacologic targeting of PPARδ inhibited tumor aggressiveness and metastasis both in vitro and in vivo." (PMID 40607925, 2025). "For PPARD, both tumor-promoting and tumor-suppressing effects have been described." (PMID 39899669, 2025). "Correlation analysis between the PPAR genes and the TME genes showed that PPARA was significantly negatively correlated with antitumor components, matrix remodeling and tumor proliferation rate, while PPARD was positively correlated with matrix composition (p < 0.05)." (PMID 38529307, 2024). "The increase in PPARδ may also promote tumor angiogenesis and progression through its effects on endothelial cells." (PMID 39195246, 2024). "Conclusively, PPARδ seems to work as a tumor promoter and may call for the development of selective antagonists to fight cancer." (PMID 37833991, 2023). "Moreover, PPARδ was found to dramatically accelerate pancreatic ductal adenocarcinoma development by activating the PPARδ-CCL2/CCR2 axis or the GOT2-PPARδ axis to drive immunosuppression through suppressing T cell-mediated anti-tumor immunity." (PMID 37572185, 2023). "However, PPARδ expression was unexpectedly found to be significantly upregulated in B cells from draining lymph nodes (dLNs) of tumor-bearing mice, while PPARγ expression was undetectable in these B cells (data not shown)." (PMID 37291146, 2023). "Additionally, PPARδ was considered to be a key regulator involving tumor metastasis, which strongly enhanced angiogenesis, epithelial-mesenchymal transition (EMT), invasion and migration." (PMID 35151320, 2022). "KAT2A and PPARD showed different expressions between tumor stage and grades." (PMID 36476410, 2022). "The TGFβ target gene, peroxisome proliferator activated receptor delta (PPARδ) seems to play a crucial role in regulating TGFβ paradox in PCa, thus PPARδ repression increases the inhibitory effect of TGFβ on tumor cells, while PPARδ induction promotes TGFβ pro-tumoral functions." (PMID 36338516, 2022). "The expression of PPARδ was closely related to the HCC tumor microenvironment." (PMID 35151320, 2022). "However, the role of PPARD in regulation of downstream metabolism in normal gastric and tumor cells is elusive." (PMID 35163565, 2022). "In order to be able to assess whether changes in PPARδ gene expression, important for tumour pathogenesis, including NSCLC, are related to changes in miR17-5p level, it is necessary to analyze the correlation between the expression level of both molecules." (PMID 34921177, 2021). "Furthermore, ectopic PPARδ signalling increases the tumour-initiating efficiency of intestinal progenitors following loss of Apc." (PMID 33673710, 2021). "Therefore, our results provide a rational for the combination therapy of PPARδ enhancers with bevacizumab in mCRC to achieve the higher frequency of tumor regressions and optimal clinical benefit." (PMID 34712608, 2021). "Comparison of the PPARδ and miR-17 expression levels between NSCLC and control tissue in the studied histotypes showed significantly lower expression values of both PPARδ and miR-17 in the tumour tissue in the AC group (p = 0.0004 and p = 0.0120; respectively, Mann–Whitney U test)." (PMID 34921177, 2021). "This implies that PPARδ may play distinct or even opposite roles depending on the tumor type and environmental context." (PMID 34712608, 2021).
tumor (continued). "Importantly, combination of thiram with PPARδ antagonist GSK3787 had synergic effect on tumor suppression." (PMID 34728628, 2021). "Indeed, the fatty acid sensor PPARδ inhibits mTORC1 and thus glycolysis, and the PPARδ antagonist GS-K3787 restores in vitro the anti-tumor function in NK cells." (PMID 34696286, 2021). "Importantly, inhibition of fatty acid-induced PPARδ activation decreased the expression of Wnt-targeting genes in tumor organoids." (PMID 32913185, 2020). "It is also interesting to examine whether zaltoprofen can selectively activate not only PPARγ, but also PPARα or PPARδ, in terms of the anti‐tumor effects of zaltoprofen." (PMID 29573200, 2018). "Consistent with this, silence of PPARδ results in cell proliferation and tumor growth." (PMID 28948004, 2017). "In contrast, PPARδ can promote tumor progression, so the antagonists of PPARδ may be the potential therapeutic targets for cancer treatment." (PMID 28948004, 2017). "It needs to further determine the physical mechanism of PPARδ on tumor development." (PMID 28948004, 2017). "Taken together, PPARδ regulates tumor progression involved in multiple signaling pathways." (PMID 28948004, 2017). "The in vitro PPARδ expression, knockdown and agonist/antagonist studies suggest that PPARδ may have a role in the survival of tumour cells in vivo." (PMID 23874790, 2013). "The occurrence of the PPARD mutation in primary cell lines but not in metastatic cell line may be also explained by deletion in PPARD loci during tumor and metastasis formation." (PMID 24391853, 2013). "The tumor promoting effects of PPARδ may be related in part to activation of PDK1, which is a PPARδ target gene in keratinocytes." (PMID 21297860, 2011). "Even though a defect in angiogenesis has not beenobserved during normal development of PPARδ-/- mice, PPARδ is specificallyrequired by tumor endothelial cells to orchestrate their proliferation anddifferentiation in an environment providing abnormal sources of growth factorsand cytokines." (PMID 19325917, 2009). "Interestingly, a tumor vascularization defect wasfound in PPARδ-/- mice with subsequent decreased progression and partialregression of tumors in this mouse model." (PMID 19325917, 2009). "PPARδ-/- mice exhibit increased keratinocyte proliferation whentreated with a tumor promoter." (PMID 19325917, 2009). "Another studyshowed that loss of PPARδ in ApcMin/+ micesignificantly reduced growth of tumors larger than a diameter of 2 mm, eventhough PPARδ deficiency did not affect overall tumor incidence." (PMID 18551185, 2008). "Contradictory evidences suggest that PPARδ can act as either a tumor suppressor or tumor promoter." (PMID 18551185, 2008). "Studies in other types ofcancer also support the hypothesis that PPARδ serves as a tumor accelerator." (PMID 18551185, 2008). "In this way, PPARδ inhibits tumor growth by inducing apoptosis or differentiation." (PMID 18584037, 2008). "The reduction in the number of tumors by eachNO-ASA isomer and the respective suppression of PPARδ expression inneoplastic cells are strikingly similar; the meta isomerreduced tumor incidence by 38% and PPARδ expression by 42%, whereasthe corresponding reduction for the para isomer was 59% and55%." (PMID 18528523, 2008). "Recent evidence supports thehypothesis that PPARδ promotes tumor progression." (PMID 18584037, 2008). "Furthermore, PPARδ activation by PPARδ ligand promotes tumor growthby inhibiting epithelial tumor cell apoptosis through activation of a VEGF autocrinesignaling loop in APCmin/+ mice." (PMID 18483618, 2008). "As for PPARγ, the integrity of the tumor suppressor APC might be essential to guarantee PPARδ normal function." (PMID 17767717, 2007). "Moreover, a decrease in PPARδ expression by nitric-oxide-donating aspirin isomers was found to be proportional to their tumour inhibitory effects in Apcmin mice." (PMID 16969348, 2006).
tumor (continued). "Thus, given the obvious disparity within the published literature, we have utilized another mouse neoplasia model to further investigate the role of PPARδ in intestinal tumourigenesis." (PMID 16672050, 2006). "In addition, other genes activated by PPARδ, such as CSF1 (colony stimulating factor 1) and REG3G (regenerating islet-derived protein 3 gamma), encode secreted proteins that recruit myeloid-derived suppressor cells to the tumor microenvironment." (PMID 40247913, 2025). "In gastric cancer, PPARD overexpression in genetically engineered mice induces invasive adenocarcinoma and chronic inflammation, highlighting its therapeutic potential but necessitating further investigation into its role in metabolism and tumor microenvironment modulation." (PMID 39922804, 2025). "Additionally, PPARδ has been identified as a critical regulatory factor in tumor metastasis." (PMID 39156976, 2024). "Thus, PPARδ negatively regulates CD8+ T-cell killing of tumor cells." (PMID 39292167, 2024). "Furthermore, engagement with agonistic anti-CD40 antibody may stimulate IL-10+ Bregs, leading to an increase in number and function in tumor-bearing mice by a mechanism largely dependent on PPARδ." (PMID 37291146, 2023). "Furthermore, treatment of tumor-bearing mice with PPARδ inhibitor could efficiently diminish the number and function of IL-10+ Bregs, and act synergistically with anti-CD40 or anti-PD1 antibody to improve antitumor immune responses." (PMID 37291146, 2023). "Therefore, the proportion of FABP5/CRABPII determines whether RA inhibits cell proliferation via the CRABPII/RAR signaling or facilitates tumor progression via the FABP5/PPARδ pathway." (PMID 35445019, 2022). "Tumor-associated myeloid cells exhibited higher transcriptional expression of molecules linked to the “find me” (G2A), “eat me” (CD93, TIM1, SCARF1, SLC2A1, GAS6, TREM2, AXL, C1QA), and downstream processing (NR1H3, ATG7, PPARG, ABCA1, PPARD, DOCK180) phases of efferocytosis." (PMID 36439171, 2022). "In addition, PPARδ was highly expressed in 40–72% HCC tumor tissues among our 191 HCC samples." (PMID 34728628, 2021). "The obtained RQ values for PPARδ gene and miR-17 were analyzed in relation to clinical features of patients: age at time of diagnosis, gender and smoking history as well as histopathological characteristics of tumours (according to pTNM and AJCC classifications and NSCLC subtypes)." (PMID 34921177, 2021). "In addition, we identified that regulation of some of the tarGenes (e.g., PRX, HIPK2, and PPARD) may be important for tumor progression." (PMID 30424545, 2018). "However, increasing evidences show that PPARδ promotes tumor growth." (PMID 28948004, 2017). "Together, our findings support that PPARδ activation triggers a comprehensive transcriptional program that modulates cellular metabolism and induces EMT in response to various starvation and tumor microenvironmental signals." (PMID 40607925, 2025). "Conversely, PPARD and PPARG showed significantly higher expression in tumor tissue samples, however, only PPARG exceeded the threshold of LogFC>1." (PMID 40860798, 2025). "ScATAC analysis identified enrichment of TF motifs for hepatic development in the fetal-I and II tumor organoids, such as HNF family members (HNF4A, 4 G, 1B, 1 A), RXRG and PPARD." (PMID 39567475, 2024). "Using narrow-down analysis, six tumor antigens (AGPS, NRAS, MTDH, PANX1, NOX4, and PPARD) were found to be related to better prognoses as well as the infiltration of antigen-presenting cells in LUAD." (PMID 38331967, 2024). "Therein, the mitochondrial enzyme glutamic-oxaloacetic transaminase-2 (GOT2) bound to fatty acid ligands and stimulated PPARδ’s transcriptional activity, leading to the spatial exclusion of CD4+CD8+ T cells from the tumor tissue." (PMID 37833991, 2023). "For example, PPARD agonist has been shown to increase SIRT1 protein levels, which is a tumor promoter in LA." (PMID 35342393, 2022).
tumor (continued). "To further explore the function of PPAR signaling pathway in tumorigenesis, we treated tumor-derived organoids with the drug FH535, which is a Wnt/β-catenin signaling pathway inhibitor and a dual PPARγ and PPARδ antagonist." (PMID 35974387, 2022). "Repression of PPARδ increases tumor cell response to TGF-β–mediated growth inhibition, and activation of PPARδ promotes TGF-β–mediated tumor growth, invasion, and migration." (PMID 34827641, 2021). "A previous study indicated that FABP5 promotes tumor angiogenesis and activates the VEGF-A pathway in HCC via the peroxisome proliferator-activated receptor d (PPARd)-dependent pathway." (PMID 34685761, 2021). "ABCA1 is a CHO efflux-related gene; PPARδ directly increases the levels of ABCA1 mRNA and membrane CHO expression, which is followed by tumor growth." (PMID 34775964, 2021). "Together, these data indicate that TRMT6/TRMT61A-mediated m1A modification enhances PPARδ protein translation, and PPARδ promotes liver CSC self-renewal and tumor growth." (PMID 34728628, 2021). "To confirm the involvement of PPARδ in regulating CPT1A, we showed that treating PT130 cells or Apc/Kras tumor organoids with PPARδ agonist GW501516 directly stimulated the expression of CPT1A and PPARGC1A (a known PPARδ target gene)." (PMID 32913185, 2020). "Activation of Wnt, a secretory glycoprotein, induces expression of PPARδ, and PGE2 signals induce PPARδ transcriptional activity via activation of the PI3K/Akt pathway and inhibit apoptosis in tumor cells." (PMID 25734181, 2015). "The ability of PPARδ to have an anti-inflammatory effect in normal cells and a proinflammatory effect in tumors is reminiscent of the dual roles of TGF-β in tumor cells." (PMID 21318167, 2010). "However, activation of the peroxisome proliferator-activated receptor-delta (PPARδ) ligand by High fat diets (HFD) or its agonist GW501516 enhances IL6/STAT3 signalling and rewires PDAC tumor microenvironment." (PMID 39806421, 2025). "Interestingly, only PPARD expression positively correlated with an EMT-related gene signature formed by ZEB1, SNAI1, and SNAI2 in the tumor." (PMID 40607925, 2025). "PPARD agonists promote the expression of platelet-derived growth factor receptor beta, platelet-derived growth factor subunit B, and the tyrosinkinase KIT to promte tumor angiogenesis and progression." (PMID 38212774, 2024). "Considering the interaction between tumor antigens and APCs, these potential antigens were further screened through the TIMER database where it was found that AGPS, NRAS, MTDH, PANX1, NOX4, and PPARD genes were positively correlated with different APCs." (PMID 38331967, 2024). "We found that PPARδ is significantly upregulated in tumor-induced IL-10+ Bregs with a phenotype of CD19+CD24hiIgDlo/−CD38lo or CD19+CD24hiIgDlo/−CD38hi in both mice and humans, and the level of PPARδ expression was correlated with their potential to produce IL-10 and to inhibit T cell activation." (PMID 37291146, 2023). "We performed multidimensional analyses on PPARA, PPARG, PPARD, PPARGC1A, and PPARGC1B, including differential expression analysis in pan-cancer, immune subtype analysis, clinical analysis, tumor purity analysis, stemness correlation analysis, and drug responses." (PMID 33029111, 2020). "In summary, PDK1 expression in the mammary gland was not oncogenic, but accelerated tumor formation in conjunction with a PPARδ agonist." (PMID 21297860, 2011). "The in vivo consequences of PDK1 transgene expression in the mammary gland, its effect on tumorigenesis, and its influence on the tumor promoting effects of PPARδ activation have not been investigated." (PMID 21297860, 2011).